NRP1 (neuropilin 1)
Diseases named in the same sentence as NRP1 in open-access papers (continued):
Sharing a sentence is not in itself a finding about the gene and the disease.
esophageal cancer (6 papers, 2017 to 2023). A primary or metastatic malignant neoplasm involving the esophagus. "CALR also upregulated neuropilin-1 expression via STAT5A in esophageal cancer cells." (PMID 35641480, 2022). "Neuropilin 1 (NRP-1) is a vascular endothelial growth factor (VEGF) co-receptor that shows increased expression in OSCC, and esophageal carcinoma." (PMID 37635248, 2023). "Further, CTSL, FURIN, NRP1 and SCARB1 gene expression levels were significantly higher in esophageal carcinoma (ESCA) samples in comparison to their normal matches." (PMID 35970857, 2022). "CALR promotes migration and invasion of esophageal cancer cells by up-regulating neuropilin-1 expression via STAT5A and neuropilin-1 is a critical downstream effector of CALR in promoting cell migration and invasion." (PMID 29228584, 2017).
head and neck squamous cell carcinoma (6 papers, 2020 to 2023). A squamous cell carcinoma that arises from any of the following anatomic sites: lip and oral cavity, nasal cavity, paranasal sinuses, pharynx, larynx, and salivary glands. "Nrp1 expression was increased in primary tumors when compared to normal tissue, including head and neck squamous cell carcinoma, renal clear cell carcinoma, thyroid carcinoma, stomach adenocarcinoma, and liver hepatocellular carcinoma." (PMID 36203599, 2022).
Hypertension (6 papers, 2013 to 2024). The presence of chronic increased pressure in the systemic arterial system. "Still, an increased expression of SVEP1, NRP1, RNASE1, QSOX1, and GKN1, along with decreased expression of XYLT2, CFH, LEP, and CETP serum levels were found in patients with hypertension." (PMID 37792298, 2023). "Furthermore, transgenic mice with the NRP1 gene deletion targeted specifically to cardiac tissue exhibited cardiac hypertrophy in the absence of systemic hypertension, demonstrating conclusively that NPR1-signaling functions as an intrinsic inhibitor of myocyte growth." (PMID 23372767, 2013).
ischemia (6 papers, 2014 to 2024). A hypoperfusion of the BLOOD through an organ or tissue caused by a PATHOLOGIC CONSTRICTION or obstruction of its BLOOD VESSELS, or an absence of BLOOD CIRCULATION. "Mice with NRP1 knocked out in cardiomyocyte and vascular smooth muscle cells demonstrate decreased survival, cardiac dysfunction, and aggravated ischemia-induced HF57." (PMID 38225249, 2024). "We found that ischemia-injured neurons were intensively receptive to NRP-1 and peaked at 24 h after OGD/R and 3 d after tMCAO." (PMID 37138283, 2023). "Data suggest that NRP-1 in the endothelial cells is up-regulated and contributes to neovascularization in post-ischemia brain." (PMID 37138283, 2023). "Besides, NRP1 expression was tightly regulated by growth factors, transcription factors, and injury, e.g., tumor necrosis factor-alpha, Prox-1, and ischemia." (PMID 36425469, 2022). "Furthermore, the mechanisms that modulate NRP1 expression in pathological contexts, such as neurodegenerative disorders or ischemia, are currently unclear and would need to be further investigated." (PMID 30623799, 2019). "We also examined the expression of NRP-1, FGF-2 and VEGF in the cortex of ischemic ipsilateral brain, and found the expression of NRP-1, FGF-2 and VEGF were increased by 7 days-ischemia compared with the sham-operated group (p<0.05; p<0.05; p<0.01)." (PMID 24979385, 2014).
multiple sclerosis (6 papers, 2014 to 2026). A progressive autoimmune disorder affecting the central nervous system resulting in demyelination. "In the murine EAE model of multiple sclerosis, the exact opposite trend was observed, with Nrp1-deficient CD4+ T cells proliferating more than Nrp1+ cells." (PMID 25343644, 2014). "Interestingly, we also detected Foxp3− Th cells that expressed NRP1 in the target organ during experimental autoimmune encephalomyelitis (EAE), an induced mouse model of autoimmune neuroinflammatory disease that is used as an analog of human multiple sclerosis." (PMID 36069030, 2022).
neuropathy (6 papers, 2016 to 2023). A disorder affecting the nervous system that manifests with pain, tingling, numbness, and/or muscle weakness. "Hence, despite the shared interactions between Nrp1 and specific AlaRS and GlyRS variants, there is a clear heterogeneity in the downstream consequences of neuropathy associated ARS1 mutations, even among mutations in the same gene." (PMID 37274211, 2023). "Nonetheless, several other neuropathy-associated mutant GlyRS proteins bind NRP1, as do CMT2N-associated alleles of AARS, suggesting that it may in some way be contributing to the disease severity and pathogenesis." (PMID 35047510, 2021). "The necessity of GlyRS binding NRP1 for the disease mechanism leading to neuropathy is called into question by the failure of NRP1 to bind ΔETAQ, a four amino acid internal deletion in GlyRS that causes a severe, early onset neuropathy in both mice and humans." (PMID 35047510, 2021). "Genetic reduction of Nrp1 in mice worsens neuropathy, whereas enhanced expression of VEGF improves motor function." (PMID 29648643, 2018). "Future studies using animal models are required to establish whether the Nrp1-AlaRS interaction occurs in vivo and how this interaction contributes to the neuropathy phenotype." (PMID 37274211, 2023). "A phase 1a clinical trial of NRP-1 antibody MNRP1685A (Vesencumab®), targeting the against VEGF-binding site of NRP-1, was well-tolerated in cancer patients, but neuropathy was noted." (PMID 32869019, 2020).
sarcoma (6 papers, 2012 to 2021). A usually aggressive malignant neoplasm of the soft tissue or bone. "High NRP1 expression correlates with reduced overall survival for sarcoma (SARC), CESC, Testicular Germ Cell Tumors (TGCT) and LUSC patients in Kaplan-Meier databases, while high TMPRSS2 mRNA in tumors associates with increased survival and better prognosis for LUAD patients." (PMID 34168096, 2021). "Our data show that sarcomas may also show an up-regulated NRP-1 as a consequence of tumour hypoxia." (PMID 23185562, 2012). "We have shown that established Rh30 and RD sarcoma cell lines cultured in the presence of the tested PRMT inhibitors have decreased expression of TNC, NRP1, MYOF, EMP1, OLFML3 and CCND1 and increased expression of the GADD45G gene." (PMID 34360791, 2021).
Stroke (6 papers, 2012 to 2025). Sudden impairment of blood flow to a part of the brain due to occlusion or rupture of an artery to the brain. "NRP1 was observed to be elevated only in the core 3 d after stroke and NDN gene was down-regulated in the PI area at 24 h." (PMID 23284893, 2012).
cardiomyopathy (5 papers, 2017 to 2025). A disease of the heart muscle or myocardium proper. "In smooth muscle cells and cardiomyocytes, NRP1 down-regulation reduces TGF-β canonical pathway, with loss of NRP1 expression in these cell types decreasing mouse survival and correlating with cardiomyopathy." (PMID 38323651, 2024). "However, diabetic female rats have reduced expression of neuropilin 1 that attenuates cardiomyopathy compared to diabetic male rats." (PMID 29259233, 2017).
cognitive decline (5 papers, 2020 to 2026). "A reduction in expression of the 'protective' VEGFR3 and co-receptors neuropilin 1 and 2 has also been recently linked to cognitive decline in AD." (PMID 41967873, 2026). "NLG4 was associated with cognitive decline, while neuropilin-1 (NRP-1) was shown to facilitate SARS-CoV-2 entry by binding to the spike protein." (PMID 36899824, 2023). "A predisposition for SARS-CoV-2 due to high NRP-1 levels, combined with an APOEε4 positive status, could be the perfect storm for increased viral load, neuroinflammation, and subsequent cognitive decline observed in AD." (PMID 40584180, 2025). "One study reported NRP1 to interact with APOE-e4 in cognition as higher levels of NRP1 correlated to cognitive decline in patients with the APOE-e4 gene." (PMID 37280551, 2023). "They revealed that high expression of NRP1 correlates to a cognitive decline in the patients carrying the APOE-ε4 gene, whereas NRP1 is associated with a beneficial outcome for patients without the APOE-ε4 gene." (PMID 32911833, 2020).
Cognitive impairment (5 papers, 2016 to 2026). Abnormal cognition is characterized by deficits in thinking, reasoning, or remembering. "Interaction of ApoE polymorphism with VEGF genes has been shown to affect cognitive impairment in AD patients as increased levels of Neuropilin 1 (NRP1), a member of VEGF family in AD patients has been shown to be associated with improved cognition in ApoE4 non-carriers." (PMID 37199411, 2023).
diabetic retinopathy (5 papers, 2011 to 2025). "In agreement with a NRP1 role in VEGF-induced permeability, a heptapeptide that blocks VEGF binding to NRP1 (see Section 6.1.2) attenuates both neovascularisation and vascular permeability in a mouse model of diabetic retinopathy." (PMID 26923176, 2016). "The purpose of this study was to evaluate the effects of an NRP-1 inhibitor, ATWLPPR peptide, on the early stages of diabetic retinopathy." (PMID 26554379, 2015). "Background literature was searched in PubMed using search terms such as ‘diabetic retinopathy’, ‘diabetic macular ischemia’, ‘diabetic macular edema’, ‘semaphorin 3a’, ‘neuropilin 1’, ‘retinal non-perfusion’, ‘vascular perfusion’, ‘anti-VEGF’, ‘corticosteroid’ and ‘laser photocoagulation’." (PMID 40634736, 2025).
fibrosarcoma (5 papers, 2014 to 2025). A malignant mesenchymal fibroblastic neoplasm affecting the soft tissue and bone. "It is therefore possible that NRP-1 may regulate pro-apoptotic processes associated with VEGF188 expression in the fibrosarcomas." (PMID 25119572, 2014). "To corroborate the identification of PLA signals as corresponding to VEGFR2/NRP1 trans‐complexes, we studied mouse fibrosarcoma where tumor cells expressed NRP1, allowing trans‐complexes to be established." (PMID 30027561, 2018). "In summary, in a mouse fibrosarcoma model, NRP1 presentation by tumor cells to the adjacent endothelium had significant effects on vessel numbers and vessel morphology, correlating with reduced tumor proliferation." (PMID 30027561, 2018). "To study the role of VEGFR2/NRP1 interactions between tumor and endothelial cells in vivo, we previously generated a T241 fibrosarcoma cell line stably expressing murine NRP1 (T241:NRP1) by lentivirus transduction." (PMID 30027561, 2018). "Unexpectedly, silencing of NRP-1 completely disrupted tumor formation in fibrosarcoma." (PMID 28320399, 2017). "In mouse fibrosarcoma, VEGFR2/NRP1 trans‐complexes correlated with reduced tumor vessel branching and reduced tumor cell proliferation." (PMID 30027561, 2018). "Instead of VEGF, in human fibrosarcoma, HIF-1α promoted VM by up-regulating Neuropilin-1 (NRP-1), a VEGF receptor and co-receptor of VEGFR-2." (PMID 28320399, 2017). "While our results cannot exclude an involvement of NRP-1 in autocrine signalling, the fact that various recombinant VEGF isoforms failed to activate pERK, pAKT or pStat3 signalling or alter the proliferation of the fibrosarcoma cells does not support such an involvement." (PMID 25119572, 2014).
Hyperglycemia (5 papers, 2014 to 2025). An increased concentration of glucose in the blood. "Decreased expression of axon guidance pathway genes, Robo1, Ntn1, Ntng1, Nrp1, and Efnb3 in NSCs exposed to hyperglycemia was suggestive that miRNAs could target and deregulate the axonal guidance pathway as predicted by the pathway analysis." (PMID 28798665, 2017). "In this present study we investigated the effect of hypoglycemia and hyperglycemia on three major classes of proteins: (i) the ligand VEGF and its receptors (VEGFR1, VEGFR2 and co-receptor Neuropilin-1), (ii) cell-cell adhesion proteins, (iii) cell to ECM adhesion proteins." (PMID 25401697, 2014). "In contrast, in the absence of Tregs, AhR activation also reduced Nrp1 expression on Th17 cells, which was consistent with our previous study demonstrating 11-Cl-BBQ reduced Nrp1+RORγt+ Th17 cells and protected NOD mice from hyperglycemia." (PMID 38035105, 2023). "Hyperglycaemia, instead of hyperinsulinaemia and hyperlipidaemia, can significantly induce the expression of SARS‐CoV‐2 entry factors (Ace2, Tmprss2, Tmprss4, Furin and Nrp1) in liver cells, but not in lung and pancreatic cells, which is attenuated by mTOR inhibition." (PMID 40442985, 2025).
kidney cancer (5 papers, 2016 to 2025). Primary or metastatic malignant neoplasm involving the kidney. "To demonstrate translocation we conjugated the biotinylated miRNAs used in the cell-free binding assays with streptavidin-coated fluorescent microparticles, and incubated them with ACHN kidney cancer cells pre-treated or not with a blocking anti-NRP1 antibody." (PMID 27486976, 2016).
migraine (5 papers, 2018 to 2022). "In a previous study, miR-378c directly targeted neuropilin 1(NRP1; Hu and Luo, 2022), NRP1 is also a migraine susceptibility gene." (PMID 36704329, 2022). "In this study, we tested the association of previously identified migraine-related SNPs in a specific MM cohort and found evidence for a potential role of rs2506142 in the Neuropilin-1 (NRP1) gene at 10p11.22 (OMIM: 602069)." (PMID 29671086, 2018). "Menstrual migraine affects a subset of female MO sufferers; replication of migraine GWAS loci in a menstrual migraine case-control cohort suggested a particular role for NRP1 in this subgroup." (PMID 31226929, 2019). "Overall these results provide evidence that while MM and other phenotypes of migraine may have some genetic commonality, including the rs2506142 NRP1 SNP, there may be distinct genetic differences." (PMID 29671086, 2018). "Therefore, NRP1 functions could be related to either the neuronal or vascular aspects of migraine pathophysiology." (PMID 29671086, 2018).
prostate tumor (5 papers, 2016 to 2024). "Finally, we showed that NRP1-Δ7 inhibited growth of prostatic tumors and their vascularization in vivo." (PMID 27798666, 2016). "It is noteworthy that NRP1 mRNA expression significantly increased in non-tumoral prostate epithelial cells HPrEC when subjected to stiffness related to a prostate tumor microenvironment (80 kPa)." (PMID 38903533, 2024).
acute leukemia (4 papers, 2013 to 2023). A clonal (malignant) hematopoietic disorder with an acute onset, affecting the bone marrow and the peripheral blood. "They concluded that NRP-1 is significantly associated with acute leukemia and that its level might serve as an indicator for disease severity and progression." (PMID 24385810, 2013). "Furthermore, the vascular effects of NRP‐1/CD304 have led to its investigation in acute leukemia." (PMID 36965095, 2023).
acute lymphoblastic leukemia (4 papers, 2013 to 2023). Leukemia with an acute onset, characterized by the presence of lymphoblasts in the bone marrow and the peripheral blood. "Neuropilin-1 expression was significantly higher in patients with pre-B acute lymphoblastic leukemia (74.04%) than patients with early pre-B ALL (23.55%)." (PMID 25574368, 2015). "The aim of this work was to study the prognostic value of Neuropilin-1 (NRP-1) expression in Egyptian children with B-lineage acute lymphoblastic leukemia (ALL)." (PMID 25574368, 2015). "Other diseases, such as T‐cell acute lymphoblastic leukemia (T‐ALL), B‐cell non‐Hodgkin lymphoma (B‐NHL), T/NK‐cell lymphoma and plasma cell neoplasms, did not express NRP‐1/CD304." (PMID 36965095, 2023). "However, there are no literature reports about the expression of NRP‐1/CD304 in other hematological diseases besides BPDCN, AML, and B‐ALL, such as T‐cell acute lymphoblastic leukemia (T‐ALL), B‐cell non‐Hodgkin lymphoma (B‐NHL), T/NK‐cell lymphoma and plasma cell neoplasms." (PMID 36965095, 2023).
Anosmia (4 papers, 2021 to 2022). An inability to perceive odors. "On the other hand, NRP1 has been implicated in Kallman syndrome, a congenital disease characterized by hypogonadism and anosmia." (PMID 35053224, 2022). "With regards to olfaction, NRP-1 has been implicated in Kallman syndrome, a congenital disease characterized by hypogonadism and anosmia." (PMID 33395426, 2021). "Further studies are thus required to confirm the role of NRP1 in SARS-CoV-2-induced anosmia and neurological manifestations." (PMID 36230989, 2022). "Together, the involvement of NRP-1 in SARS-CoV-2 entry and its association with anosmia support the presence of an alternative route of SARS-CoV-2 entry and CNS manifestation." (PMID 36230989, 2022). "The high expression of NRP-1 in a variety of olfactory cells and its importance in olfactory neuronal maintenance makes it a stronger candidate in the mechanism of anosmia, compared to ACE2." (PMID 33395426, 2021). "Anosmia could even be a harbinger of another SARS-CoV-2 sequelae, i.e., the NRP-1-facilitated infiltration of this virus into the CNS." (PMID 33395426, 2021).
brain cancer (4 papers, 2021 to 2025). A primary or metastatic malignant neoplasm affecting the brain. "NRP1 is expressed in many cancers, such as brain cancers, and is associated with poor prognosis." (PMID 34277411, 2021). "The ongoing progress in experimental therapy will likely allow the development of a pipeline of NRP1 inhibitors feasible for clinical testing in patients with brain cancers." (PMID 37894289, 2023). "The case of NRP1 highlights the potential of regulators of neurodevelopment as biomarkers and therapeutic targets in brain cancer." (PMID 37894289, 2023). "In this article, we review the current knowledge on the expression and role of NRP1 in brain cancers and its potential as a target in experimental neurooncology." (PMID 37894289, 2023). "The aim of this review is to highlight the involvement of NRP1 in pediatric brain cancers, focusing essentially on the roles of NRP1 in cancer stem cells and in the regulation of the immune system." (PMID 34277411, 2021). "To conclude, NRP1, through its different action ways, could be a key protein in the progression of pediatric brain cancers, and could be envisaged as a therapeutic target for these tumors." (PMID 34277411, 2021). "We reviewed the role of neuropilin-1 (NRP1), a transmembrane glycoprotein that directs neuronal migration during development, in brain cancer types that afflict children or adults." (PMID 37894289, 2023). "Its best known involvement is in angiogenesis, but this review focuses on the role of NRP1 in cancer stem cells (CSC) and in immune system (SI) during brain cancers development." (PMID 34277411, 2021).
chronic obstructive pulmonary disease (4 papers, 2019 to 2023). A chronic and progressive lung disorder characterized by the loss of elasticity of the bronchial tree and the air sacs, destruction of the air sacs wall, thickening of the bronchial wall, and mucous accumulation in the bronchial tree. "For example, Neuropilin-1+ human LTi cells are present in inducible bronchus-associated lymphoid tissue (iBALT) in the inflamed lung in chronic obstructive pulmonary disease (COPD)." (PMID 31507605, 2019). "Recently, VEGF-B overexpressed mice (under dobutamine stress) as well as VEGF-B186 and soluble VEGF-R1 transgene co-delivery in pigs were shown to induce cardiac arrhythmias, suggesting the role of NRP-1 in the growth of sympathetic nerves and subsequent cardiac arrhythmias." (PMID 36552897, 2022). "It has been reported that human neuropilin-1(NRP1)+ LTi-like ILC3s were observed in lung tissues from patients with chronic obstructive pulmonary disease, which may participate in ectopic lymphocyte accumulation." (PMID 33193381, 2020). "During pulmonary pathogenesis in chronic obstructive pulmonary disease (COPD), human NRP-1+ ILC3 located in proximity to blood vessels and lung ectopic lymphoid tissues, where they induced VCAM-1 and ICAM-1 expression on mesenchymal stromal cells, and efficiently responded to VEGF-A." (PMID 37234993, 2023). "However, recent findings in mice and porcine studies using mutant unsplicable VEGF-B186 did not support the role of NRP-1 in provoking cardiac arrhythmias." (PMID 36552897, 2022).